NOTCH1 (notch receptor 1)
Diseases named in the same sentence as NOTCH1 in open-access papers (continued):
Sharing a sentence is not in itself a finding about the gene and the disease.
tumor (continued). "On the other hand, subgroups of HNSCC patients with activating, or gain-of-function NOTCH1 mutations have been observed as well, and these may show worse prognosis than tumours with wild-type NOTCH16." (PMID 37607974, 2023). "Notably, primary CLL samples derived from patients carrying BIRC3 mutations (n = 3) or NOTCH1 mutations (n = 1) in their CLL tumor cells were particularly sensitive to NIK inhibition." (PMID 35326640, 2022). "In a third, follow-up study, the group surmised that CCR7 activation turned on the Notch1 signaling pathway with concomitant elevation of the cancer stem cell population and thus loss of CCR7 produced attenuated Notch1 responses, reduced stem cell numbers and slowed tumor formation and growth." (PMID 35203305, 2022). "In PDAC, USP18 was considered as a tumor promoter and possess significant prognostic value whose overexpression could promote cell proliferation through removing K48-linked ubiquitin from Notch-1 and activating Notch-1/c-Myc signaling pathway." (PMID 36582601, 2022). "Furthermore, these data also hint on the importance of the tumor microenvironment for NOTCH1 activation, suggesting that mutations of oncogenes still rely on signals from non-malignant cells to fully unfold their detrimental effects." (PMID 36266281, 2022). "To assess whether NOTCH1 mutations can be detected in blood, we measured circulating tumor DNA (ctDNA)." (PMID 36124629, 2022). "Two tumor suppressor genes NOTCH1 and FAT1 both have a high nonsense mutation rate in HNSCC." (PMID 36428516, 2022). "In addition, we explored the role of the lethal giant disc (Lgd) in tumor suppression and its association with Notch1 in CML cells." (PMID 35847841, 2022). "Simultaneously, the results of the transcriptome analysis presented recurrent tumors with NOTCH1 mutation displayed upregulation of the cell cycle pathway, along with decreased B cells score, T cells score, immune signature score and tumor-infiltrating lymphocytes (TILs) score." (PMID 35911687, 2022). "The mutation observed in this study as predicted by the prediction softwares (SIFT, PolyPhen2 and Mutation Taster) was deleterious suggesting that NOTCH1 p.V1699E mutation might confer loss of function and its ability to suppress tumour might be lost." (PMID 35350997, 2022). "Therefore, VEGF-mediated tumor-associated angiogenesis and activated Notch1 signal-driven tumor survival are among the most important molecular mechanisms contributing to HCC recurrence and progression." (PMID 36212390, 2022). "Immunohistochemical analyses of Notch1 in OSCCs showed that its positivity in tumor cells was significantly associated with advanced clinical staging, lymph node metastasis, histopathological tumor classification, tumor invasion, and locoregional recurrence." (PMID 33854547, 2021). "Particularly, we found that Notch1 deficiency triggered tumor cell accumulation inside the bronchiolar lumen and expression of the Hippo pathway transcription factor TAZ, which may represent a target for cancer therapy in this specific subgroup of lung ADCs." (PMID 34257546, 2021). "Moreover, NOTCH1 loss-of-function mutations were found to specifically promote tumour persistence in sporadic BCCs suggesting therapeutic restoring of the NOTCH tumour-suppressor function as a potential approach to eradicate persistent tumour cells." (PMID 34168209, 2021). "Thus, in mammary epithelium, Notch1 can function as an oncogene in cooperation with Pik3caE545K and Pik3caH1047R, but as an allele-specific tumor suppressor in cooperation with Pik3caH1047R." (PMID 34475389, 2021).
tumor (continued). "Among these alterations, we identified KMT2B S421P and NOTCH1 T2483 missense mutations, which may have an important role in pathogenesis of this tumor model given the previously established role of these genes in tumorigenesis." (PMID 34051734, 2021). "Furthermore, the enhanced expression and activation of Notch1 was associated with a passage-dependent increase of Bcl-2 levels and downregulation of p21, thus promoting survival and cell cycle progression of tumor spheres." (PMID 33922104, 2021). "These available data imply that NOTCH1, owing to certain mutational events, may act as a tumor suppressor in head and neck epithelium." (PMID 33822486, 2021). "The specific selection of otherwise rare, gain-of-function NOTCH1 mutations in Chinese HNSCC patients may be related to different tumour aetiology, as well as specific genetic and environmental factors in these populations." (PMID 34944837, 2021). "Moreover, the reduced cell contact inhibition, caused by the induced TAZ expression upon Notch1 deficiency followed by the Hippo pathway alteration, facilitates protruding of proliferating tumor cells from the bronchiolar lining." (PMID 34257546, 2021). "Given that most of these NOTCH1 mutations are related to a loss of function, NOTCH1 may play a role as tumor suppressor in SeC-EOs." (PMID 34638295, 2021). "In addition, tumor biomarkers such as expression of NOTCH1, tumor hypoxia, and genetic variants in genes such as TGFβ1, COX7A1, and TBX5 have also been shown to be associated with prognosis in HPV-related HN cancer." (PMID 34830844, 2021). "Integration of the Mouse Mammary Tumour Virus (MMTV) into the Notch1 or Notch4 loci, leading to the expression of an activated form of the respective Notch proteins, had been shown to disrupt mammary gland development and cause tumour development." (PMID 34295896, 2021). "F-box/WD repeat-containing protein 7, FBXW7, mediator complex subunit 12 (MED12), and spen family transcriptional repressor (SPEN), three tumor suppressors associated with the regulation of the NOTCH1 pathway, were also identified as being mutated with low frequency in CLL." (PMID 32182763, 2020). "In addition, combination therapy of GSI with DOX reduced the PC-3 PCSC-derived tumor growth in vivo, which was associated with the decreased Notch-1 expression in tumor tissues." (PMID 32586404, 2020). "This prompted us to investigate the impact of activating NOTCH1 mutations on tumor angiogenesis." (PMID 31676012, 2019). "In addition, the analysis of clonal evolution also revealed NOTCH1 mutation was the most common somatic mutation detected in recurrent tumor samples." (PMID 30850667, 2019). "Studies with pharmacological compounds or with classical knockout or conditional mouse lines revealed that loss-of-function (LOF) of Dll4, Notch1 or Rbpj results in severe vascular developmental defects and a marked delay in tumour growth due to an abnormal increase in angiogenesis." (PMID 31043605, 2019). "We observed a high NOTCH1 mutation rate in plasma in comparison to tumor tissue, which may reveal a role of NOTCH1 modifications in tumor metastasis and highlight the clinical advantage of the plasma in detecting mutation biopsy." (PMID 31369215, 2019). "Indeed, Notch1 mutations present in 10% of lung cancers, are associated with poor prognosis and promote tumor initiation." (PMID 30873026, 2019). "Notably, many detached epithelial structures were located in the colonic sub-mucosa of VN-/- mice and in the MUC2+ cysts (yellow arrows), suggesting that Notch-1-deficient epithelial cells have acquired motility and tumor invasion properties." (PMID 30323897, 2018). "As a result, the oncogenic role of specific Notch1 mutations in tumor progression is still speculative and requires further verification." (PMID 29321718, 2018).
tumor (continued). "For example, the hub gene of NOTCH1, encoding one of the four Notch receptors, has an important role in a signaling pathway that is involved in multifaceted regulation of cell survival, proliferation, tumor angiogenesis, and metastasis." (PMID 28500316, 2017). "While activation of Notch1 is able per se to suppress NET tumor growth and is associated with reduction of NET tumor markers, SSTR2 up-regulation has been used to synergistically increase the cytotoxicity of a SSTR-targeting camptothecin-somatostatin conjugate." (PMID 27418145, 2016). "Furthermore, the Pim inhibitor DHPCC-9 efficiently reduced Notch1-induced tumor growth to the same level as the SA mutation." (PMID 27281612, 2016). "Furthermore, we demonstrate that the spectrum of tumour-acquired mutations is representative of that found in tumour biopsies, for example in the case of NOTCH1-3." (PMID 27693639, 2016). "Strong NOTCH1 expression was associated with earlier tumor stages (p = 0.043; pmax = 0.061)." (PMID 25954607, 2015). "Thus different mutations to the same protein (NOTCH1) lead to its involvement in different tumor types through distinct mechanisms." (PMID 26353933, 2015). "Notch-1 has been implicated in tumor metastasis in a variety of cancer types." (PMID 25990317, 2015). "In addition, the case with a NOTCH1 codon 2444 nonsense mutation in 42% of sequencing reads subsequently recurred as a tumor with wild type NOTCH1 alleles." (PMID 23825651, 2013). "From 10% to 18% of CLLs have been reported to have NOTCH1 gain-of-function mutations in prior studies; thus, the frequency of NOTCH1 activation as judged by NICD1 staining in our tumor cohort greatly exceeds what would be expected if activation were confined to CLLs with NOTCH1 mutations." (PMID 23825651, 2013). "In 12 of these 13 cases, we noted that NICD1 staining was much weaker in tumor cells in perinodal soft tissue than it was within tumor cells in the immediately adjacent lymph node, including one case associated with a the NOTCH1 codon 2514 del(CT) in 35% of sequencing reads." (PMID 23825651, 2013). "The aberrant Notch1 expression in both ICC tissues and ICC cells suggests that increased Notch1 expression might be associated with tumor progression." (PMID 23688168, 2013). "Taken together, aberrant Notch1 expression in both ICC tissues and ICC cells suggests that increased Notch1 expression might be associated with tumor progression." (PMID 23688168, 2013). "Based on these findings, we believe that inactivation of Notch-1 signaling by As2O3 leads to inactivation of its target gene expression, which could be mechanistically linked with As2O3-mediated tumor suppressor function." (PMID 22949821, 2012). "However, Notch-1 has been implicated in not only the self-renewal of these tumour-initiating cells, but also in trastuzumab resistance." (PMID 21847123, 2011). "The correlations of NF-κB and Notch1 with lymph node involvement, lymphatic vessel density (LVD), podoplanin, and vascular endothelial growth factor-C (VEGF-C) were further evaluated to determine the association of NF-κB and Notch1 expression with tumor-induced lymphangiogenesis." (PMID 21939555, 2011). "Also, Notch1 has been implicated in the estradiol-induced increase in microvessel density in vivo and therefore in estradiol-increased tumor angiogenesis in MCF7 cells and HUVEC." (PMID 20011585, 2009). "Additionally, tumor-adjacent tissues contained higher numbers of immune cells—including tumor-associated macrophages, alveolar macrophages, and NK cells—with elevated NOTCH1 expression, indicating potential immune cell recruitment into tumors via chemotactic signals." (PMID 41184502, 2025).
tumor (continued). "In addition, this anti-tumor effect may be associated with a reduction in key factors that promote tumor development such as Notch-1, Hes-1, VEGF, and MMPs." (PMID 39183411, 2024). "Another unknown variable, essential for understanding how NOTCH mutations modulate disease biology is the length of time a tumor cell resides in one tissue before migrating to another, which will impact on the activation of NOTCH1 in tumor cells as signaling is cell-contact dependent." (PMID 36266281, 2022). "Additionally, in many types of squamous cancers, such as squamous cell carcinoma of the head and neck, skin, oral cavity, and esophagus, 10–20% of tumor cases harbor inactivating mutations in the Notch1 gene, and many studies suggest the tumor-suppressive roles of Notch1 in these squamous cancers." (PMID 33976158, 2021). "Furthermore, miR-34a encapsulated in chitosan/PLGA nanoparticles inhibited tumor growth in murine xenograft models of human multiple myeloma disease since this miRNA directly downregulates proteins associated with tumor development, i.e., Bcl-2, Notch 1, and CDK6." (PMID 35011442, 2021). "Similarly, the analysis of the frequency of loss-of-function mutations on DYRK2 and/or NOTCH1 in tumours showed that mutations on DYRK2 and NOTCH1 occur very rarely together, suggesting that both proteins might be in the same pathway." (PMID 31605148, 2020). "However, an alternative hypothesis states that signaling serving as tumor-suppressor in keratinocytes, is derived from the microenvironment as a response to Notch1 loss." (PMID 32796631, 2020). "The detection of FBXW7 mutation by cfDNA during post-operative follow-up and the emerging NOTCH1 mutation in the recurrent tumor samples highlight that Notch signaling pathway might be an important therapeutic target for stage III CRC patients in adjuvant setting." (PMID 30850667, 2019). "Furthermore, DLL4 stimulation of NOTCH1-mutated Mino cells enhanced tumor cell migration and angiogenesis, which could be abolished by treatment with OMP-52M51." (PMID 31676012, 2019). "However, due to the low sensitivity of the anti-Notch1 antibody, we were unable to convincingly conclude whether Notch1 is expressed in ECs or tumor-associated fibroblast cells." (PMID 29545603, 2018). "Moreover, the greater possibility of a larger (>5 cm) tumor size (OR = 0.59, 95%CI: 0.41 to 0.85), positive tumor metastasis (OR = 0.42, 95%CI: 0.24 to 0.73) and positive microvascular invasion (OR = 0.53, 95%CI: 0.31 to 0.88) were linked with high Notch 1 expression in HCC." (PMID 29093570, 2017). "However, our results were in contrast to findings from other studies mainly performed in Asian countries, which have reported a contribution of higher expression of NOTCH1 or NOTCH2 to tumor progression and, in particular, an association of higher expression of NOTCH1 with worse prognosis." (PMID 25954607, 2015). "NFIB expression positively correlated with neuroendocrine (NE) markers and contributed to tumor heterogeneity, a process modulated by Notch1." (PMID 42001853, 2026). "Deletions affecting genes like NOTCH1 (Neurogenic Locus Notch Homolog Protein 1) on chromosome 9q34.3 are commonly observed, leading to dysregulated signaling cascades and accelerated tumor progression." (PMID 41537310, 2026).
tumor (continued). "DATS suppresses Notch signaling by upregulating tumor-suppressive microRNAs (miR-34a, miR-143, miR-145, and miR-200b/c) and downregulating Notch1 and its downstream target genes." (PMID 41602823, 2026). "Notch receptors exert context- and subtype-specific roles: Notch1 and 4 promote tumour aggressiveness, whereas Notch2 often exhibits tumour-suppressive roles." (PMID 41894035, 2026). "In tumor tissues, the expression levels of Notch1 and Hes1 were dramatically upregulated in the IL-6 group." (PMID 41602823, 2026). "Today, much debate persists regarding a putative oncogenic role in HNSCC as well, with reports that NOTCH1 signaling drives tumor growth and a cancer stem cell (CSC) phenotype." (PMID 41989846, 2026). "Non–cell death functions of caspase-4 including cell division (via modulation of actin dynamics) and tumor angiogenesis (via Notch1 signaling regulation), have also been identified." (PMID 39866724, 2025). "The master transcriptional factors of MES state cells, such as c-MYC, PRRX1 and NOTCH1 were highly upregulated in the resistant tumor cells, together with the SCP marker S100B and stem cell markers KIT and SALL4." (PMID 40962798, 2025). "The NOTCH1 signaling pathway mediates cellular processes including proliferation, differentiation, apoptosis, invasion, and migration of tumor cells." (PMID 40530904, 2025). "On the other side, several mutational landscape of the NOTCH gene family (particularly NOTCH1 and NOTCH3), observed in a subset of SCLC, supports a context-dependent tumor-suppressive role." (PMID 40563292, 2025). "Collectively, these data highlight the potent anti-tumor effects of the simultaneous inhibition of the Notch1 and JAK1/STAT3 pathways." (PMID 40019515, 2025). "Western blotting confirmed successful YTHDF1 knockdown and consequent NOTCH1 downregulation in tumor tissues following VNP-siYTHDF1 treatment." (PMID 41423446, 2025). "In contrast, NOTCH1 enhances tumor invasiveness and therapeutic resistance by maintaining tumor stem cell properties and promoting angiogenesis." (PMID 41425851, 2025). "NOTCH1 has been revealed as a tumour suppressor; in contrast, NOTCH2 and NOTCH3 have demonstrated an oncogenic role in BCa." (PMID 41008920, 2025). "Ectopic expression of PDGF‐D also increased the levels of NF‐κB p‐p65, NOTCH1, and mesenchymal markers in the tumor tissues, and these changes were reversed by DAPT treatment." (PMID 40530904, 2025). "Studies have shown that Notch1 can regulate the EMT process in tumor cells by cross talking with several EMT-related transcription and growth factors (Snail, Slug, Twist1, and FGF, etc.)." (PMID 40630953, 2025). "Collectively, these data demonstrate that CRTC1 promotes tumor growth and PD-L1 expression in vitro through the Notch1/Akt pathway." (PMID 40977688, 2025). "In adaptive immunity, KLF4 inhibits the proliferation of CD8+ T cells and B cells through transcriptional repression of pro-survival and cell cycle-promoting genes such as NOTCH1 while also acting as a tumor suppressor." (PMID 40831570, 2025). "Notch1 expression was detected in the tumor and stromal cells in 92% of the cases, while CD10 expression was seen in 31% of tumor cells 79% of stromal cells of the included cases." (PMID 40060224, 2025). "NOTCH1 is a key component of the Notch signaling pathway, which has been shown to act as either an oncogene or a tumor suppressor depending on tissue context, and is recurrently altered in hematologic and epithelial malignancies." (PMID 41470046, 2025). "Several studies suggest that alterations in the oncogene NOTCH1 can act either as tumor-promoting or tumor-suppressing, depending on the cell type." (PMID 40881676, 2025). "MiR-34b, a tumor suppressor miRNA, plays a crucial role in regulating various genes involved in cellular processes, such as MET, MYC, and NOTCH1, which are implicated in brain injury." (PMID 39129166, 2025).